CCL18 (C-C motif chemokine ligand 18)
Diseases named in the same sentence as CCL18 in open-access papers (continued):
Sharing a sentence is not in itself a finding about the gene and the disease.
breast carcinoma (continued). "A recent study showed that CCL18 from activated macrophages induced epithelial–mesenchymal transition of breast cancer cells through the activation of NF-kB pathway." (PMID 29670110, 2018). "GM‐CSF‐activated macrophages in turn induce EMT in breast cancer cells, in a CCL18‐dependent mechanism, establishing a potential local feedback regulation." (PMID 28599100, 2017). "This suggests the importance of a positive feedback loop between GM-CSF and CCL18 in breast cancer metastasis." (PMID 28567162, 2017). "In breast cancer cell lines, CCL18 derived from TAMs activates NF‐κB and thereby induces EMT‐like changes including spindle‐shaped morphology, E‐cadherin‐to‐vimentin switch, and increased invasive properties." (PMID 28599100, 2017). "In five independent breast cancer online data sets, CCL18 mRNA was increased in the tumor relative to normal tissue and significantly increased in two data sets." (PMID 28290464, 2017). "Of these chemokines, only CCL18 mRNA was significantly higher in breast cancer than the paired adjacent normal tissue." (PMID 28290464, 2017). "In human breast cancer xenograft models, blocking CCL18-mediated recruitment of naive T cells into tumors reduces TI Tregs and inhibits tumor progression." (PMID 28290464, 2017). "In breast cancer, CCL18 production by TAMs promotes angiogenesis and thus supports tumour growth and dissemination." (PMID 28501938, 2017). "Reciprocally, these TAMs provide the cancer cells with increased amounts of the chemokine CCL18, which maintain the mesenchymal phenotype of the breast cancer cells, thus promoting breast cancer metastasis." (PMID 27191257, 2016). "CCL18 is a chemokine C-C motif ligand that is up-regulated in breast cancer determining the severity of breast cancer malignancy." (PMID 27152840, 2016). "In contrast, in patients with breast cancer, pancreatic cancer, cutaneous T-cell lymphoma, and lung cancer, elevated CCL18 in cancer tissues or body fluid indicates a worse clinical outcome." (PMID 26919103, 2016). "Excessive production of CCL18 in tumor-infiltrating macrophages was demonstrated in gastric cancer, breast cancer, colorectal cancer, and cutaneous T-cell lymphoma via CCL18 and CD68 co-immunostaining." (PMID 26919103, 2016). "Our present study further reveals that M2 macrophages can reduce the expression of miR98 and miR27b in breast cancer cells through the secretion of CCL18." (PMID 26244871, 2015). "Our present study has shown that CCL18 reduces the expression of miR98 and miR27b in breast cancer cells via the N-Ras/ERK/PI3K/AKT/NFκB/Lin28b signaling cascade." (PMID 26244871, 2015). "In vivo, miR98 represses CCL18-promoted metastasis and enhances the survival rate of mice with breast cancer xenografts." (PMID 26244871, 2015). "In our present study, miR-27b abrogated CCL18-induced migration and invasion of breast cancer cells by silencing Lin28b, and led to increased mature miR98 to block CCL18 signaling." (PMID 26244871, 2015). "Western blot analysis indicated that transfection with miR98, but not the mock or negative control, inhibited the activation of the N-Ras/ERK/PI3K/NFκB/Lin28b signaling pathway induced by CCL18 in breast cancer cells." (PMID 26244871, 2015). "Results from our previous study revealed that CCL18, the most abundant and specific chemokine produced by TAMs in breast cancer stroma, promotes adherence to the extracellular matrix and enhances the invasiveness of breast cancer cells." (PMID 26416449, 2015). "We further performed in vivo studies with CAMs, as well as breast cancer xenografts in NOD/SCID mice to assess the potential effects of CCL18 on angiogenesis." (PMID 26416449, 2015). "We have also demonstrated that CCL18 induces the epithelial-mesenchymal transition (EMT) in breast cancer via activation of the NFκB pathway." (PMID 26244871, 2015).
breast carcinoma (continued). "We previously demonstrated that CCL18, which is a characteristic C-C chemokine and an inflammatory cytokine that is secreted by alternatively activated M2 macrophages, promotes breast cancer metastasis and is inversely correlated with patient prognosis." (PMID 26244871, 2015). "The association between CCL18+ TAM counts and the clinicopathological status of patients with breast cancer was then analyzed." (PMID 26416449, 2015). "Our previous study showed that CCL18, the most abundant chemokine produced by TAMs in breast cancer, promotes breast cancer metastasis." (PMID 26244871, 2015). "It is well established that CCL18 induces EMT in breast cancer cells by activating the Raf/FAK/MAPK, PI3K/AKT and NFκB pathways." (PMID 26244871, 2015). "Collectively, these data suggest that reduction in miR98 contributes to CCL18 promoted breast cancer metastasis in vivo." (PMID 26244871, 2015). "Double immunohistochemical staining for CCL18 and CD34/CD31/vWF was performed in 80 breast cancer samples to study the correlation between CCL18+ TAMs and microvascular density (MVD)." (PMID 26416449, 2015). "Previously, we reported that CCL18 is a major cytokine released by TAMs and enhances breast cancer cell metastasis; moreover, CCL18 and CD68 colocalization in breast cancer tissues confirmed that CCL18-immunopositive cells represent a subset of macrophages." (PMID 26416449, 2015). "Data from our previous studies showed that PITPNM3 is a putative receptor for CCL18 on the surface of breast cancer cells and that it mediates the effects of CCL18 by activating both the ERK and Akt/GSK-3β signaling pathways in cancer cells." (PMID 26416449, 2015). "It has been shown that mesenchymal-like breast cancer cells secrete GM-CSF to activate macrophages to a CCL18-expressing TAM-like phenotype and, reciprocally, these TAM-like macrophages sustain the EMT of cancer cells." (PMID 26243145, 2015). "Our previous studies showed that CCL18 activates the PyK2-Src-FAK-ERK/PI3K signaling cascade in breast cancer cells, while N-Ras and Lin28b locate upstream and downstream, respectively, of this cascade." (PMID 26244871, 2015). "In this study, we found that CCL18 immunostaining in TAMs was proportional to the MVD in breast cancer samples, which correlated with tumor metastasis and poor prognosis." (PMID 26416449, 2015). "To determine the effect of CCL18 on miRNA expression in breast cancer cells, we performed miRNA microarray analysis for MDA-MB-231 breast cancer cell line 24 hr after exposure to CCL18 or co-cultured with IL-4 stimulated M2 macrophages." (PMID 26244871, 2015). "Elevated CCL18 expression plays a role in ovarian carcinoma and induces metastasis of breast cancer." (PMID 24934728, 2014). "And more importantly, we found that CAFs would be able to promote breast cancer cell invasion under co-culture condition through up-regulated CCL18." (PMID 23577100, 2013). "In addition, the acetylation of ACAP4 at Lys311 ensures the dynamic cycling of the ARF6-ACAP4 complex with the plasma membrane and is essential for CCL18-induced breast cancer cell migration and invasion." (PMID 39744421, 2025). "For instance, IHC analysis of breast cancer biopsies has shown a high abundance of CCL18 + TAMs in patients resistant to chemotherapy, highlighting a positive correlation between the infiltration of CCL18 + TAMs and CD10 + GPR77 + CAF." (PMID 39068459, 2024). "TAM-derived CCL18-PITPNM3 axis promotes breast cancer metastasis." (PMID 39199574, 2024). "However, we treated breast cancer cells MCF-7 with recombinant CCL18 for 2 weeks, and then challenged the tumor cells with docetaxel or cisplatin." (PMID 36418470, 2023). "CCL18 is an important gene in breast cancer, and the CNV of CCL18 may reduce immune cell infiltration." (PMID 36805828, 2023). "Breast cancer patients with higher expression of CCL18 and TRGC1 had poorer survival." (PMID 36805828, 2023).
breast carcinoma (continued). "We found that the CCL18+ cell density in the tumor samples from chemoresistant patients (n = 103) was dramatically higher than that from responsive patients (n = 156), implying that CCL18 participates in breast cancer chemoresistance." (PMID 36418470, 2023). "In addition, MCF-7 breast cancer cells cocultured with CCL18-activated NBFs generated significantly more mammospheres." (PMID 36418470, 2023). "Furthermore, a previous study reported that naïve CD4 + T cells are recruited and converted to Treg cells by macrophages-derived CCL18 in breast cancer." (PMID 36221095, 2022). "One of which, CC chemokine ligand 18 (CCL18), known to be released by tumor-associated macrophages (TAMs), was found to be associated with extensive angiogenesis, both in vitro and in vivo in breast cancer." (PMID 35159163, 2022). "Moreover, high expression of GM-CSF is associated with the prevalence of CCL18-secreting macrophages and the realization of EMT by breast cancer cells." (PMID 35847899, 2022). "The anti-CCL18 antibody could disrupt the GM-CSF-CCL18 feedback loop to treat cancer metastasis, especially breast cancer metastasis." (PMID 33435254, 2021). "It has been reported that isolated TAMs from breast cancer tissues produce high amounts of pro-tumor cytokines, including CCL18, CCL17, CCL22, and IL-10 and reveal a CD206high/human leukocyte antigen-DRlow phenotype relating to the TME immunosuppressive phenotype." (PMID 33129234, 2021). "CCL18 produced by TAMs is an essential regulator of angiogenesis in breast cancer." (PMID 34209679, 2021). "In addition, expression of the ACKR6 ligand CCL18 positively correlates with microvessel density/tumor angiogenesis in breast cancer." (PMID 32456359, 2020). "Moreover, breast cancer cell intravasation was induced through integrin clustering via CCL18 from TAMs in breast cancer cell lines and human breast cancer tissue." (PMID 32726950, 2020). "CCL18 is expressed and released by TAMs in large quantities in human breast cancer." (PMID 32456359, 2020). "Interestingly TAMs isolated from breast cancers have previously been seen to secrete large amounts of CCL18 and promote metastasis through CCL18 binding to PITPNM357." (PMID 33149188, 2020). "Importantly, CCL18 expression correlated with invasive behaviour and poor survival in patients with breast cancer." (PMID 32825277, 2020). "Furthermore, the TAMs in breast cancer produce large amounts of CCL18, which promotes breast cancer metastasis through the PITPNM3 receptor." (PMID 33224886, 2020). "Testing this type of NP at various dimensions, the group demonstrated that the largest NPs (180 nm) delivered siRNA and induced CCL18 silencing in TAMs with higher efficacy than the other sizes, leading to substantial inhibition of breast cancer cell migration." (PMID 33322132, 2020). "CCL18 released from TAMs promoted breast cancer metastasis via PITPNM3." (PMID 32456359, 2020). "Despite the observed differences in secreted VEGF/CCL-18 levels, we still asked whether hM2a macrophages influence breast cancer cell migration and invasion through synergistic VEGF/CCL-18 signaling, and if this process proceeds through ROCK signaling." (PMID 31214501, 2019). "In breast cancer, TAMs-expressed CCL18 forming a positive feedback loop induces cancer cell EMT." (PMID 31629410, 2019). "Moreover, macrophage-derived CCL18 was reported to create a feedback loop between macrophage and breast cancer cells by stimulating breast cancer-derived GM-CSF." (PMID 31126309, 2019). "Therefore, it can be confirmed that CCL18 signaling is the main target of IL-32θ to inhibit the macrophage-induced metastasis of breast cancer cells." (PMID 31126309, 2019). "Moreover, TAMs can promote breast cancer cell migration by secreting CCL18 to upregulate PITPNM3 of cancer cells." (PMID 31629410, 2019).
breast carcinoma (continued). "Blocking CCL18 during co-culture of macrophages and breast cancer cells reduced the levels of breast cancer progression-related factors and PKCδ downstream signaling suggesting CCL18 as the main macrophage-secreted factors triggering the signaling pathway inhibited by IL-32θ." (PMID 31126309, 2019). "However, our data show the novel finding of synergy between VEGF and CCL-18 signaling in their ability to enhance breast cancer motility and invasiveness." (PMID 31214501, 2019). "Among the factors secreted by macrophages, CCL18 was reported to have strong effects on breast cancer progression whereas macrophage-secreted IL-1β, TNF-α, and CCL5 were previously suppressed by IL-32θ; thus, mRNA expression levels of these factors were measured." (PMID 31126309, 2019). "Additional studies have shown that CCL18-induced breast cancer metastasis occurs through the Pyk2 receptor, Pyk2 N-terminal domain interacting receptor 1 (Nir1), and that Nir1 expression is associated with lymph nodes and distant metastasis in patients with invasive breast cancer." (PMID 29738483, 2018). "Inhibition of GM-CSF or CCL18 significantly reduces breast cancer metastasis." (PMID 28356139, 2017). "In previous studies it could be demonstrated that CCL18 enhances invasiveness and malignancy and promotes angiogenesis in breast cancer tissue." (PMID 28957436, 2017). "Moreover, adoptively transferred human naive CD4+ T cells infiltrate human breast cancer orthotopic xenografts in a CCL18-dependent manner." (PMID 28290464, 2017). "GM-CSF was highly expressed in about 29% of human breast cancer samples, and the infiltration of CCL18-positive macrophages was often observed at the invasive front of tumors, where cancer cells displayed more mesenchymal features and expressed high levels of GM-CSF." (PMID 26834744, 2016). "In contrast, increased CCL18 expression indicates a poor prognosis in breast cancer." (PMID 26919103, 2016). "CCL18 is predominantly produced by M2 macrophages, and increased expression of CCL18 is observed in infiltrating macrophages in ovarian cancer, cutaneous T-cell lymphoma, gastric cancer, and breast cancer." (PMID 26919103, 2016). "Therefore, CCL18 signaling is critical to the interaction between breast cancer cells and their microenvironment, which leads to breast cancer metastasis." (PMID 26244871, 2015). "Taken together, our results suggested that CCL18 promotes angiogenesis in breast cancer." (PMID 26416449, 2015). "Additionally, quantification of human hypoxanthine phosphor-ribosyl transferase (HPRT) mRNA also demonstrated that CCL18 increased the number of metastatic breast cancer cells in the lungs and livers of the xenografted mice by 3-fold." (PMID 26244871, 2015). "To further investigate whether miR98 or miR27b is involved in CCL18 promoted migration and invasion of breast cancer cells, we used Boyden chamber assay to measure the migration and invasion of MDA-MB-231 cells." (PMID 26244871, 2015). "Quantitatively, the MVD was proportional to the CCL18+ TAM count in breast cancer tissues." (PMID 26416449, 2015). "Therefore, we evaluated the role of CCL18 released from TAMs in promoting angiogenesis in breast cancer tissues." (PMID 26416449, 2015). "To investigate whether CCL18 reduces miR98 expression at transcriptional or post-transcriptional level, we employed qRT-PCR to detect the primary and mature miR98 expression in MCF-7 breast cancer cells treated with CCL18 (20 ng/ml) for 1 hr to 14 days (d)." (PMID 26244871, 2015). "To determine the role of miR98 and miR27b in CCL18-promoted breast cancer metastasis, we transfected miR98 or miR27b mimics or their negative controls into MDA-MB-231 or MCF-7 cells, and determined by qRT-PCR that the reduction of miR98 or miR27b was reversed by the miRNA mimics (data not shown)." (PMID 26244871, 2015).
breast carcinoma (continued). "Furthermore, GM-CSF produced by human breast cancer cell lines induces CCL18 secretion from cultured macrophages, suggesting that macrophage-cancer cell interaction establish gradients of these chemokines in the tumor microenvironment." (PMID 26275794, 2015). "We have demonstrated that the presence of chemokine (C-C motif) ligand 18 (CCL18), a hallmark of M2 macrophages, promotes breast cancer metastasis through binding to its receptor PITPNM3 on breast cancer cells; this chemokine is also associated with a poor prognosis of patients with breast cancer." (PMID 26244871, 2015). "In conclusion, our findings suggest that CCL18 released from TAMs promotes angiogenesis and tumor progression in breast cancer; thus, CCL18 may serve as a novel target for anti-angiogenic therapies." (PMID 26416449, 2015). "Next, we further evaluated whether CCL18 promoted migration and invasion of breast cancer cells could be inhibited by N-Ras or Lin28b suppression." (PMID 26244871, 2015). "We found that the expression of N-Ras protein was increased in MCF-7 breast cancer cells that were treated with CCL18 for 1 hr, and the phosphorylation of ERK at Thr202 and Tyr204, PI3K P85 at Tyr458 and Akt at Ser473 was concurrently induced and remained active for 7 d." (PMID 26244871, 2015). "However, M2 macrophages that were transfected with CCL18 siRNAs or treated with CCL18- neutralizing antibodies lost their ability to reduce miR98 expression in both breast cancer cell lines (P < 0.05)." (PMID 26244871, 2015). "In in vitro experiments, the group showed that the invasiveness of MDA-MB-231 cells and primary breast cancer cells was enhanced equally by the addition of recombinant CCL18 and coculture with TAMs, whereas the addition of anti-CCL18 and CCL18-siRNAs reduced the number of invasive cancer cells." (PMID 25165728, 2014). "CAFs could promote breast cancer cell invasion under co-culture conditions through up-regulated CCL18 and CXCL12." (PMID 23577100, 2013). "PITPNM3/Nir1 was recently described to be a signaling receptor for CCL18 on breast cancer cells." (PMID 23874339, 2013). "However, the CCL18-dependent activation of NF-κB can be inhibited by IL-32θ in breast cancer cells." (PMID 33114763, 2020). "Thus CCL18 expression by TAMs recruits naive CD4+ T cells to orthotopic breast cancer xenografts." (PMID 28290464, 2017). "However, it remains unclear whether miRNAs are involved in CCL18 signaling pathway in breast cancer cells to promote tumor metastasis." (PMID 26244871, 2015). "Therefore, high CCL18+ TAM infiltration may correlate with low miR98 expression in breast cancer, which is in agreement with the in-vitro data." (PMID 26244871, 2015). "Therefore, down-regulation of miR98 contributes to CCL18 related breast cancer progression." (PMID 26244871, 2015). "However, it remains unclear whether microRNAs (miRNAs), which may modulate multiple cellular pathways, are involved in the regulation of CCL18 signaling and the ensuing metastasis of breast cancer." (PMID 26244871, 2015). "However, MDA-MB-231 breast cancer cells that were transfected with miR98 or miR27b mimics had a significant reduction in their migration and invasion abilities by approximately 60% or 70%, respectively, upon treatment with CCL18 (Figure SF, SG)." (PMID 26244871, 2015). "The identification of PITPNM3/Nir1 as a PTX-sensitive cell surface receptor responsible for the CCL18 induced migration of human breast cancer cells indicated that this could be the receptor for this chemokine on leukocytes, but unfortunately we have shown that this seems not to be the case." (PMID 23874339, 2013). "Cochrane’s Q test did not provide evidence of heterogeneity between CCL1 (p = 0.227), CCL2 (p = 0.982), CCL18 (p = 0.221), CXCL5 (p = 0.533), CXCL12 (p = 0.977), and CXCL13 (p = 0.520) and breast cancer." (PMID 38075694, 2023). "The recruited TAMs further secrete reciprocating CCL18 to induce EMT and promote breast cancer metastasis." (PMID 37880742, 2023).